SCARB1 (scavenger receptor class B member 1)
Description:
Receptor for different ligands such as phospholipids, cholesterol ester, lipoproteins, phosphatidylserine and apoptotic cells. Receptor for HDL, mediating selective uptake of cholesteryl ether and HDL-dependent cholesterol efflux. Also facilitates the flux of free and esterified cholesterol between the cell surface and apoB-containing lipoproteins and modified lipoproteins, although less efficiently than HDL. May be involved in the phagocytosis of apoptotic cells, via its phosphatidylserine binding activity. (Microbial infection) Acts as a receptor for hepatitis C virus in hepatocytes and appears to facilitate its cell entry. Binding between SCARB1 and the hepatitis C virus glycoprotein E2 is independent of the genotype of the viral isolate. (Microbial infection) Mediates uptake of M.fortuitum, E.coli and S.aureus. (Microbial infection) Facilitates the entry of human coronavirus SARS-CoV-2 by acting as an entry cofactor through HDL binding.
Synonyms: SRB1; CLA-1; CD36L1; CLA1; SR-BI; HDLCQ6; HDLQTL6
Tractability: Small molecule: a high-quality ligand is known; it belongs to a druggable protein family. Antibody: UniProt places it where antibodies can reach, with high confidence; its Gene Ontology location is reachable by antibodies, with high confidence; UniProt predicts a signal peptide or a membrane-spanning region. PROTAC: ubiquitination databases record sites on it; its protein half-life has been measured; a small molecule that binds it is known.
Target class: Membrane receptor
Chemical probes: ML278, ML279, ML312
Gene: Protein-coding gene on chromosome 12 (124,776,856 to 124,882,668, reverse strand). Ensembl gene ENSG00000073060.
Subcellular location: Cell membrane; Membrane, caveola
Subcellular location (Human Protein Atlas): Vesicles; Lysosomes; Rods & Rings
Pathways (Reactome):
Transport of small molecules: HDL clearance
Vesicle-mediated transport: Scavenging by Class B Receptors
Gene Ontology:
Molecular function: apolipoprotein A-I binding; apolipoprotein binding; high-density lipoprotein particle binding; high-density lipoprotein particle receptor activity; lipopolysaccharide binding; lipopolysaccharide immune receptor activity; low-density lipoprotein particle binding; protein binding; 1-phosphatidylinositol binding; lipid binding; phosphatidylserine binding; scavenger receptor activity; amyloid-beta binding
Biological process: adhesion of symbiont to host; cholesterol efflux; cholesterol import; detection of lipopolysaccharide; high density lipoprotein particle mediated signaling; high-density lipoprotein particle clearance; lipopolysaccharide transport; positive regulation of cholesterol storage; positive regulation of nitric oxide-cGMP mediated signal transduction; positive regulation of sphingolipid mediated signaling pathway; recognition of apoptotic cell; reverse cholesterol transport; vasodilation; vitamin transmembrane transport; cholesterol homeostasis; high-density lipoprotein particle remodeling; low-density lipoprotein particle clearance; phospholipid transport; plasma lipoprotein particle clearance; positive regulation of endothelial cell migration; positive regulation of triglyceride biosynthetic process; regulation of phagocytosis; regulation of phosphatidylcholine catabolic process; triglyceride homeostasis; wound healing; and 2 more
Cellular component: extracellular exosome; lysosomal membrane; plasma membrane; caveola; cell surface; endocytic vesicle membrane; cytoplasm; membrane
Genetic constraint (gnomAD): Loss-of-function variants: 29 observed, 55.72 expected, observed/expected ratio (o/e) 0.52, 90% interval 0.39 to 0.71. The upper end of that interval is the gene's LOEUF score, 0.71, which puts it in group 2 of 6, group 1 being the genes least tolerant of losing a copy. Missense variants: 537 observed, 675.95 expected, observed/expected ratio (o/e) 0.79, 90% interval 0.74 to 0.85. Synonymous variants: 246 observed, 271.13 expected, observed/expected ratio (o/e) 0.91, 90% interval 0.82 to 1.01.
Homologues: Orthologues: macaque SCARB1 (91% identical), chimpanzee SCARB1 (90% identical), dog SCARB1 (82% identical), rabbit SCARB1 (82% identical), pig SCARB1 (81% identical), mouse Scarb1 (80% identical), rat Scarb1 (76% identical), guinea pig SCARB1 (75% identical), tropical clawed frog scarb1 (55% identical), zebrafish scarb1 (52% identical), Drosophila melanogaster emp (28% identical), Drosophila melanogaster dsb (26% identical), and 3 more. Paralogues in human: SCARB2 (30% identical), CD36 (29% identical).
Diseases named in the same sentence as SCARB1 in open-access papers:
SCARB1 is named in the same sentence as 189 diseases in open-access papers, as found by Europe PMC text mining. Sharing a sentence is not in itself a finding about the gene and the disease. The quoted sentences say what the papers report.
atherosclerosis (171 papers, 2005 to 2026). A disease characterized by the build-up of fatty material and calcium deposition in the arterial wall resulting in partial or complete occlusion of the arterial lumen. "Specifically, Scarb1 deficiency in LysM-Cre expressing cells increased atherosclerosis by increasing the expression of the apoptosis inhibitor of macrophages (AIM) protein and consequently reducing macrophage apoptosis." (PMID 40672317, 2025). "In the Multi-Ethnic Study of Atherosclerosis (MESA), we showed that the common noncoding rs10846744 SNP within SCARB1 was significantly associated with increased subclinical atherosclerosis and incident MI risk." (PMID 33398433, 2021). "In the post-transcriptional regulation, some miRNAs, which target SCARB1 and suppress its expression, are associated with cholesterol accumulation underlying atherosclerosis." (PMID 34940525, 2021). "This review summarizes the progress in studying the genomic variants of ABCA1, ABCG1, and SCARB1, and the regulation of their function at transcriptional and post-transcriptional levels in atherosclerosis." (PMID 34940525, 2021). "Previous studies in mice and humans have implicated the lipoprotein receptor SCARB1 in association with atherosclerosis and lipid levels." (PMID 25993026, 2015). "Since Scarb1 regulates HDL cholesterol levels, its decrease has been associated with increased susceptibility to atherosclerosis: Scarb1 KO mice showed elevated HDL cholesterol and reduced selective HDL cholesterol clearance." (PMID 25379707, 2014). "The rs10846744 SNP of the SCARB1 gene is also associated with atherosclerosis in multiple ethnic populations, including African American (P=0.03), Chinese (P=0.02), European American (P=0.05) and Hispanic populations (P=0.03)." (PMID 23404648, 2013). "However, it has recently been shown that patients with a rare genetic inactivation of the SCARB1 also develop high levels of HDL-C associated with a higher atherosclerosis risk." (PMID 27207171, 2016). "We recently reported the association of the intronic SCARB1 SNP rs10846744 with subclinical atherosclerosis and incident CVD, and a nearby SNP was also reported among those reaching the FDR threshold of 5% in a recent large-scale GWAS of CHD from the CARDIOGRAMplusC4D consortium." (PMID 25993026, 2015). "Additionally, The genotype of lipoprotein scavenger receptor BI (SCARB1) rs10846744 associated with atherosclerosis and atherosclerotic cardiovascular disease was also related to alteration of sLAG3 level, suggesting that sLAG3 level was susceptible to alteration of gene." (PMID 36247429, 2022). "We showed that the scavenger receptor class B type I gene (SCARB1) intronic rs10846744 SNP was significantly associated with subclinical atherosclerosis (SCA) as measured by common carotid intima-media thickness (cIMT) in participants from the Multi-Ethnic Study of Atherosclerosis (MESA)." (PMID 30289950, 2018). "Whereas earlier reports indicate that deletion of Scarb1 reduced the development of atherosclerosis, another study showed that deletion of this receptor in monocytes and macrophages worsened the extension of atherosclerotic lesions at earlier stages." (PMID 40672317, 2025). "The role of SCARB1 in macrophages has been extensively studied in mouse models of atherosclerosis where it has been found to be both pro-atherogenic and anti-atherogenic." (PMID 40672317, 2025). "The Pcolce2 knockout yielded a phenotype like that reported for Scarb1-KO mice, which also exhibit increased atherosclerosis despite elevated plasma HDL levels." (PMID 39374805, 2024). "The endothelial-specific Scarb1 overexpression reduces atherosclerosis by increasing cholesterol clearance rate via endothelial RCT." (PMID 35464770, 2022). "The endothelial-specific Scarb1 knockout, on the other hand, reduces atherosclerosis by inhibiting the vv neovascularization that is essential for atherogenesis in the mouse model." (PMID 35464770, 2022).
atherosclerosis (continued). "Inhibition of scavenger receptor class B member 1 expression induced by DNMT3b accelerated atherosclerosis in foam cells." (PMID 35422896, 2022). "Reversely, overexpression of Scarb1 is associated with lower plasma levels of HDL-C and attenuated progression of atherosclerosis." (PMID 35097019, 2021). "While the biochemical events in the RCT pathway have been studied thoroughly, it is still not clear how changes in the functioning of ABCA1, ABCG1, and SCARB1 affect atherosclerosis progression." (PMID 34940525, 2021). "In LDL receptor–deficient mice, attenuated expression of SCARB1 was associated with increased LDL-C and accelerated atherosclerosis." (PMID 29113374, 2017). "In various animal models, overexpression of SCARB1 reduced blood lipids and ameliorated atherosclerosis." (PMID 29113374, 2017). "Studies have shown that SCARB1 facilitates lipoprotein metabolism and decreases atherosclerosis in mice." (PMID 29113374, 2017). "The importance of SCARB1 in reverse cholesterol transport and atherosclerosis has been previously confirmed in mouse models." (PMID 26754576, 2016). "A recent study found that SCARB1 rs10846744, associated with Lp-PLA2 activity in our study, was associated with subclinical atherosclerosis in the Multi-ethnic Study of Atherosclerosis." (PMID 20442857, 2010). "Similarly, another study reported that EC-specific Scarb1 KO mice exhibited reduced progression of atherosclerosis, which aligns with our cardioprotective findings." (PMID 40772900, 2025). "Thus, SR-B1 represents a possible correlation between atherosclerosis and osteoporosis, suggesting that SCARB1 contributes to the regulation of bone metabolism." (PMID 37107290, 2023). "Our goal was to determine whether genetic variability in three candidate phospholipase-related genes, namely PLA2G7, SCARB1 and PLA2G4A, was associated with atherosclerosis and the occurrence of CV events in a population of nephrosclerosis patients." (PMID 35586043, 2022). "On the other hand, complete (whole-body) knockout of Scarb1 increases atherosclerosis in apoE−/− mice (Scarb1−/−, apoE−/−) as a result of impaired RCT, and humans who are homozygous for a rare loss-of-function mutation of Scarb1 are 1.8 times more likely to develop coronary heart disease." (PMID 35464770, 2022). "Conversely, overexpression of SCARB1 in mouse models reduces atherosclerosis." (PMID 33801586, 2021). "Thus, lncRNA MALAT1 affects the expression of SCARB1 as a result of interaction with other proteins, contributes to its transcription activation, and prevents atherosclerosis development." (PMID 34940525, 2021). "Scarb1 knockout in mice resulted in higher HDL-C and increased risk of atherosclerosis." (PMID 35097019, 2021). "In addition, the disruption of Scarb1 gene in atherosclerotic mice (APOE -/-) accelerates the onset of atherosclerosis." (PMID 25379707, 2014). "Another study indicated that SCARB1 null female mice experience accelerated atherosclerosis." (PMID 23404648, 2013). "Therefore, the endothelial-specific Scarb1 knockout may have reduced aortic neovascularization and consequently, reduced atherosclerosis." (PMID 35464770, 2022).
atherosclerosis (continued). "The impaired molecular machinery we observed—including reduced expression of receptors (Scarb1) and transporters (Abca1, Abcg1)—strongly suggests a functional deficit in the lymphatic RCT pathway in advanced atherosclerosis." (PMID 41465071, 2025). "Knockdown of DOCK4 suppressed SR-B1–dependent LDL transcytosis in cultured cells, and both Scarb1 and DOCK4 mRNA levels were increased in the atherosclerosis-prone lesser curvature of mouse and human aortic arch." (PMID 40013359, 2025). "In mice, the systemic or liver-specific KO of Scarb1 led to severe hyperlipidemia characterized by the increase of HDL, LDL, and remnants, as well as atherosclerosis." (PMID 39393447, 2024). "In the scavenger receptor B1 (Scarb1) knockout mice, the atheroprotective HDL-C levels are elevated but—(apparently) paradoxically—atherosclerosis is increased." (PMID 27207171, 2016). "In endothelial cells, SCARB1 mediates LDL transcytosis and promotes atherosclerosis." (PMID 40672317, 2025). "SCARB1 rs10846744 is significantly associated with Lp-PLA2 activity, atherosclerosis, and CVD events, but Lp-PLA2 activity is not a mediator in the association of rs10846744 with cIMT in MESA." (PMID 30289950, 2018). "Many of the genes differentially regulated during monocyte-to-macrophage differentiation (downregulated genes include JAK2, STAT6, TLR8, and TLR2, and upregulated genes include VEGFB, TGFB1, FN1, IL-1R2, SCARB1, MSR1, and CD163) have been previously reported in the pathogenesis of atherosclerosis." (PMID 25011540, 2014). "Scavenger receptor class B member 1 (SRB1) facilitates efferocytosis via the SRC-PI3K-RAC1 pathway, and its deletion in macrophages results in defective efferocytosis, increased plaque size, larger necrotic core area, and heightened inflammation in atherosclerosis." (PMID 39660125, 2024). "A variant with a similar phenotype (HDL-raising but also associated with CHD) was recently identified in the SCARB1 gene providing further evidence that high HDL-C is not protective and may in some circumstances promote atherosclerosis." (PMID 27549350, 2016).
coronary heart disease (35 papers, 2009 to 2025). "For instance, certain genetic mutations in LIPC and SCARB1, which have been linked to a higher risk of coronary heart disease." (PMID 39696353, 2024). "The concentration of HDL-C in people with partial deletion of the SCARB1 gene is significantly higher and the risk of coronary heart disease is 80% higher than those in normal people." (PMID 39835260, 2024). "In humans, SCARB1 serves as an important mediator of cholesterol homeostasis, and mutations in SCARB1 are associated with accelerated development of coronary artery disease." (PMID 37398667, 2023). "SCARB1 rs10846744 was associated with coronary artery disease events in CARDIoGRAMplusC4D (odds ratio 1.05; 95% CI [1.02, 1.07]; P = 1.4x10-4)." (PMID 30289950, 2018). "Several studies have reported that the SCARB1 rs5888 SNP is associated with the development of coronary heart disease, and lipid profile." (PMID 19806217, 2009). "In summary, it was found that SCARB1 gene polymorphisms may contribute to the genetic susceptibility to coronary heart disease, and various study results support the beneficial effects of SCARB1 on human cardiovascular health." (PMID 35087605, 2022). "These genes included Cdh13 and Lpl from Cluster 1; Nfia, Col4a1 and Serpinh1 from Cluster 2; Arhgef12, Col4a2, Scarb1 and Cst3 from Cluster 3; Pecam1 and Aldh2 from Cluster 4, providing plausible molecular basis for the inextricable causal link between age and coronary artery disease." (PMID 35615560, 2022). "In the current study, we sought to examine association of SCARB1 missense single nucleotide polymorphism (SNP) rs4238001 with incident coronary heart disease (CHD)." (PMID 25993026, 2015). "Other mechanisms explaining the association of high HDL-C and CVD, include genetic variants, e.g. CETP, ABCA1, LIPC, SCARB1, that lead to extremely high HDL-C concentrations and a higher risk of coronary artery disease and death." (PMID 41239356, 2025). "It is important to note that the interactions between F2 rs3136441, LPA rs55730499, STARD3 rs881844, SCARB1 rs838880, and COBLL1 rs12328675 showed a strong contribution to the risk of coronary artery disease." (PMID 35203469, 2022). "Loss-of-function mutations in the gene encoding SR-BI (SCARB1) cause an increase in HDL-C but do not reduce the risk of coronary artery disease." (PMID 34440638, 2021).
breast cancer (30 papers, 2013 to 2026). A primary or metastatic malignant neoplasm involving the breast. "Exosomal miR-6803 internalized into cancer cells promotes proliferation, metastasis and stemness by targeting its specific SCARB1 gene in breast cancer." (PMID 40707430, 2025). "Consistently, the overexpression of Scarb1 also inhibited the role of exosomes in promoting the proliferation and migration of breast cancer cells." (PMID 40707430, 2025). "These miRNAs are shuttled from fibroblasts to breast cancer cells mediated by exosomes and then inhibit their target gene, SCARB1, which subsequently leads to breast cancer malignant progression." (PMID 40707430, 2025). "Next, a set of experiments in vitro and in vivo were conducted to further confirm that miR-6803b targets Scarb1 to promote breast cancer progression." (PMID 40707430, 2025). "First, the knockdown of Scarb1 imitated the promotion of miR-6803b on breast cancer cell proliferation, migration and invasion, EMT development and stemness." (PMID 40707430, 2025). "In breast cancer, miR-6803b targets the SCARB1 gene to inhibit its expression and then promote cancer cell metastasis, resulting in cancer progression." (PMID 40707430, 2025). "Expression of SR-B1 receptor, SCARB1 mRNA, and consequently SR-B1 protein levels are induced by hypercholesterolemia in mouse models of breast cancer and are connected to aggressiveness of cancer." (PMID 39243069, 2024). "Here, we also show a significant upregulation of another lipoprotein receptor, SCARB1, in human CE-rich breast carcinomas." (PMID 26055977, 2015). "Notably, we also found that miR-6803b promotes breast cancer proliferation and metastasis by targeting Scarb1 in vivo." (PMID 40707430, 2025). "Moreover, SCARB1 has been reportedly upregulated by hypercholesterolemia in a breast cancer mice model." (PMID 26055977, 2015). "Our results demonstrate that ATG7 expression in fibroblasts has a crucial role in modifying stromal–epithelial crosstalk and disrupting homeostasis in the TME and reveal that ATG7 in fibroblasts and SCARB1 in breast cancer cells may be new indicators for the diagnosis of breast cancer." (PMID 40707430, 2025). "Finally, using GEO database (GSE21422) and Kaplan‒Meier plotter online web tool revealed that SCARB1 expression was significantly decreased in breast cancer, and a high expression of SCARB1 was significantly associated with worse OS, RFS and DMFS for BRCA patients." (PMID 40707430, 2025).